EEF1E1 (eukaryotic translation elongation factor 1 epsilon 1)
Description:
Positive modulator of ATM response to DNA damage.
Synonyms: AIMP3; P18
Tractability: Small molecule: a structure with a bound ligand is known. PROTAC: ubiquitination databases record sites on it; its protein half-life has been measured.
Gene: Protein-coding gene on chromosome 6 (8,073,360 to 8,102,573, reverse strand). Ensembl gene ENSG00000124802.
Subcellular location: Cytoplasm; Cytoplasm, cytosol; Nucleus
Subcellular location (Human Protein Atlas): Cytosol; Nucleoplasm
Pathways (Reactome):
Developmental Biology: Transcriptional and post-translational regulation of MITF-M expression and activity
Metabolism: Selenoamino acid metabolism
Metabolism of proteins: Cytosolic tRNA aminoacylation
Gene Ontology:
Molecular function: protein binding
Biological process: positive regulation of cellular senescence; negative regulation of cell population proliferation; positive regulation of apoptotic process; tRNA aminoacylation for protein translation
Cellular component: aminoacyl-tRNA synthetase multienzyme complex; cytosol; nucleoplasm; cytoplasm; nucleus
Genetic constraint (gnomAD): Loss-of-function variants: 13 observed, 15.3 expected, observed/expected ratio (o/e) 0.85, 90% interval 0.55 to 1.35. The upper end of that interval is the gene's LOEUF score, 1.35, which puts it in group 5 of 6, group 1 being the genes least tolerant of losing a copy. Missense variants: 157 observed, 169.9 expected, observed/expected ratio (o/e) 0.92, 90% interval 0.81 to 1.05. Synonymous variants: 63 observed, 69.4 expected, observed/expected ratio (o/e) 0.91, 90% interval 0.74 to 1.12.
Homologues: Orthologues: chimpanzee EEF1E1 (100% identical), dog EEF1E1 (95% identical), pig EEF1E1 (93% identical), guinea pig EEF1E1 (91% identical), mouse Eef1e1 (87% identical), rabbit EEF1E1 (74% identical), rat Eef1e1 (68% identical), tropical clawed frog eef1e1 (67% identical), zebrafish eef1e1 (60% identical).
Diseases named in the same sentence as EEF1E1 in open-access papers:
EEF1E1 is named in the same sentence as 36 diseases in open-access papers, as found by Europe PMC text mining. Sharing a sentence is not in itself a finding about the gene and the disease. The quoted sentences say what the papers report.
hepatocellular carcinoma (6 papers, 2018 to 2025). A malignant tumor that arises from hepatocytes. "In hepatocellular carcinoma (HCC), EEF1E1 expression is associated with various immune cells, including Tregs and Th17 cells, suggesting its potential as a prognostic marker." (PMID 39683528, 2024). "EEF1E1 has been reported to play a role in ovarian cancer, breast cancer, non-small cell lung cancer and other cancers, but its role and mechanism in hepatocellular carcinoma is still unclear." (PMID 34282404, 2021). "In this study, we used TCGA and UCSC databases to analyze the differential expression of EEF1E1 in hepatocellular carcinoma (HCC) tissues and its correlation with clinicopathological features." (PMID 34282404, 2021). "EEF1E1 has been reported to play a role in ovarian cancer, breast cancer, non-small cell lung cancer and other cancers, but its role and mechanism in hepatocellular carcinoma (HCC) are still unknown." (PMID 34282404, 2021). "Recent studies have further revealed the unique role of the translation elongation factor EEF1E1 in HCC, where it forms condensates within the cell through LLPS, activating the PTEN/AKT signaling pathway and significantly enhancing the DNA damage repair capacity of hepatocellular carcinoma cells." (PMID 41280670, 2025). "In addition, using qPCR, we found that the mRNA expression of EEF1E1 and HDAC2 in hepatocellular carcinoma cells (HepG2, Huh6, and SNU398) are higher than those in normal hepatocytes (LO2)." (PMID 36189258, 2022).
lung carcinoma (4 papers, 2018 to 2024). "Likewise, increased transcript levels of EEF1G and EEF1E1 led to poor OS and FP in lung cancer." (PMID 29342219, 2018). "Overexpression of many factors predicted poor prognosis in breast (EEF1D, EEF1E1, EEF2) and lung cancer (EEF1A2, EEF1B2, EEF1G, EEF1E1)." (PMID 29342219, 2018). "Overexpression of most factors predicted a poor prognosis in breast (EEF1D, EEF1E1, and EEF2) and lung cancer (EEF1A2, EEF1B2, EEF1G, EEF1E1) in KM analysis." (PMID 29342219, 2018).
colorectal cancer (3 papers, 2018 to 2022). A primary or metastatic malignant neoplasm that affects the colon or rectum. "SurvExpress analysis revealed significantly reduced mRNA levels of EEF1A1, EEF1B2, EEF1E1, EEF1G and EEF2 in the high-risk group, in colorectal cancer and, predicted poor survival." (PMID 29342219, 2018). "Eukaryotic translation elongation factor 1 epsilon 1 (EEF1E1) has been identified as a putative tumor suppressor due to its downregulation in gastric and colorectal cancer." (PMID 29342219, 2018).
liver cancer (3 papers, 2018 to 2022). An epithelial or non-epithelial malignant neoplasm that arises from the liver. "TCGA liver cancer patient characteristics and EEF1E1 expression correlated with clinical-pathological characteristics (cox regression)." (PMID 34282404, 2021). "For liver cancer, Oncomine analysis revealed that transcript levels of only EEF1E1 were significantly elevated in tumor tissues in Roessler’s datasets." (PMID 29342219, 2018). "Using the HPA database, we found that the protein expression level of EEF1E1 and HDAC2 were higher in liver cancer while lower in normal liver." (PMID 36189258, 2022).
ovarian carcinoma (3 papers, 2018 to 2021). A malignant neoplasm originating from the surface ovarian epithelium. "Regarding EEF1E1, studies have found that EEF1E1 is overexpressed in most tumors, including ovarian cancer, and that high expression of EEF1G predicts better OS and PFS rates in OC patients, which is consistent with our research results." (PMID 34825509, 2021). "Oncomine analysis for ovarian cancer revealed significant difference of mRNA levels between tumor and normal samples, for EEF1A1, EEF1A2 and EEF1E1 only." (PMID 29342219, 2018).
astrocytoma (2 papers, 2018 to 2025). "As for EEF1E1, two analyses in Shai’s datasets showed that it was upregulated in astrocytoma and oligodendroglioma." (PMID 29342219, 2018).
Burkitt lymphoma (1 paper, 2018). A rare form of malignant mature B-cell non-Hodgkin lymphoma. "EEF1E1 mRNA was overexpressed in two datasets, i.e. Basso’s for Burkitt's lymphoma and, Brune’s for diffuse large B-Cell lymphoma." (PMID 29342219, 2018).
chromophobe renal cell carcinoma (1 paper, 2018). Chromophobe renal cell carcinoma is a rare subtype of renal cell carcinoma, originating from the intercalating cells of the collecting ducts and macroscopically manifesting as a well-circumscribed, highly lobulated, solid tumor that is usually diagnosed at an early stage. "EEF1E1 was found to be downregulated in chromophobe renal cell carcinoma compared to normal tissue, in Yuseknko’s dataset." (PMID 29342219, 2018).
colon adenocarcinoma (1 paper, 2018). "A previous report has cited EEF1E1 as a tumor suppressor gene in gastric and colon adenocarcinoma." (PMID 29342219, 2018).
diabetes (1 paper, 2018). "MiR-375 has been reported to inhibit diabetes by targeting the expression of mRNA targets of miR-375 such as Gephyrin (GPHN), Insulin induced gene 2 (INSIG2), Myotrophin (MTPN) and Eukaryotic translation elongation factor 1 (Eef1e1)." (PMID 30379973, 2018).
kidney clear cell carcinoma (1 paper, 2018). "As per TCGA analysis, expression levels of EEF1A1, EEF1B2, EEF1G, EEF1D and EEF2 were significantly upregulated in kidney clear cell carcinoma while that of EEF1E1 was downregulated." (PMID 29342219, 2018).
large cell lung carcinoma (1 paper, 2018). "Like EEF1A2, EEF1E1 transcript levels were also consistently elevated in small cell lung carcinoma, lung carcinoid tumor and squamous cell lung carcinoma subtypes as per Bhattacharjee’s study and, in large cell lung carcinoma, according to Hou’s dataset." (PMID 29342219, 2018).
mucinous adenocarcinoma (1 paper, 2018). An invasive adenocarcinoma composed of malignant glandular cells which contain intracytoplasmic mucin. "EEF1E1 transcript levels on the other hand, were significantly upregulated in four different datasets (Skrzypczak, Kaiser, Hong, Skrzypczak) for rectal mucinous adenocarcinoma subtype." (PMID 29342219, 2018).
myocardial infarction (1 paper, 2017). Gross necrosis of the myocardium, as a result of interruption of the blood supply to the area, as in coronary thrombosis. "In the myocardial infarction (MI) model a significant increase in Fstl1 expression at one and two weeks after MI was found when normalizing the data with the validated reference genes Eef1e1 and Rpl4 (F = 6.348, p = 0.011)." (PMID 28154421, 2017).
ovarian serous adenocarcinoma (1 paper, 2018). An adenocarcinoma that arises from the ovary and is characterized by the presence of malignant epithelial cells that, in well differentiated tumors, resemble the epithelium of the fallopian tube or, in poorly differentiated tumors, show anaplastic features and marked nuclear atypia. "EEF1E1 mRNA levels were upregulated in ovarian serous adenocarcinoma in Yoshivara’s study." (PMID 29342219, 2018).
pancreatic cancer (1 paper, 2018). "In pancreatic cancer, the mRNA levels of EEF1A1, EEF1A2, EEF1B2, EEF1D and EEF1E1 were found to be significantly downregulated, as shown by Oncomine analysis." (PMID 29342219, 2018).
prostate carcinoma (1 paper, 2018). A carcinoma that arises from epithelial cells of the prostate gland. "Furthermore, increased expression of EEF1E1 in prostate carcinoma was indicated in Tomlin’s dataset as well." (PMID 29342219, 2018).
sarcopenia (1 paper, 2024). Progressive decline in muscle mass due to aging which results in decreased functional capacity of muscles. "Further studies are warranted to demonstrate the direct causal relationships between SIRT1 and autophagy, as well as SIRT1 and EEF1E1, and their roles in sarcopenia and cellular senescence." (PMID 39276001, 2024). "In the present study, case–control research has demonstrated that plasma levels of EEF1E1 are correlated with sarcopenia, skeletal muscle index and muscle strength." (PMID 39276001, 2024). "This study revealed the viability of HIIT as an effective strategy for the prevention and management of sarcopenia and underscored the potential of EEF1E1 as a candidate for therapeutic targeting." (PMID 39276001, 2024). "This study highlights the potential of HIIT as a promising approach to prevent and treat sarcopenia while also highlighting EEF1E1 as a potential intervention target." (PMID 39276001, 2024). "Furthermore, although siRNA, overexpression and recombinant EEF1E1 interventions aided in validating the role of EEF1E1 in sarcopenia, further research, possibly using EEF1E1 knockout mice, would be advantageous." (PMID 39276001, 2024). "We explored the relationship between a HIIT‐specific protein relative to MICT, identified via comparative proteomic analysis, eukaryotic translation elongation factor 1 epsilon 1 (EEF1E1) and sarcopenia in a paired case–control study of elderly individuals (aged over 65)." (PMID 39276001, 2024). "Furthermore, in the older adults, irrespective of sarcopenia status, a notable association was found between heightened levels of EEF1E1 in the plasma and a decrease in skeletal muscle mass, muscular strength and physical performance." (PMID 39276001, 2024). "Furthermore, our research confirmed a negative association between EEF1E1 levels in the skeletal muscle and sarcopenia through animal and in vitro experiments, consistent with previous reports that identified skeletal muscle as the primary source of circulating EEF1E1." (PMID 39276001, 2024). "We subsequently investigated EEF1E1, a modulator of the ATM response to DNA damage that is involved in the regulation of cellular senescence and has not been previously linked to sarcopenia." (PMID 39276001, 2024). "In a separate study analysing sarcopenia cases and controls, it was observed that older adults suffering from sarcopenia exhibited higher plasma levels of EEF1E1 compared to their counterparts without sarcopenia." (PMID 39276001, 2024).
tumor (18 papers, 2012 to 2025). "As for the most prevalent pathological characteristics: tumor grade, tumor T stage and tumor clinical stage, the high expression of EEF1E1 had significant relationship with worse grade and advanced stage (p < 0.0001 and p < 0.05, respectively)." (PMID 38972883, 2024). "EEF1E1 mRNA and protein expression in tumor was statistically higher than normal (EEF1E1 mRNA: p < 0.001; EEF1E1 protein: p < 0.01)." (PMID 34282404, 2021). "Mann Whitney U test showed that EEF1E1 expression in the tumor was higher than normal, the median difference between the two groups was 0.812 (0.671-0.951), the difference was statistically significant (p < 0.001)." (PMID 34282404, 2021). "AIMP3, also known as eukaryotic translation elongation factor 1 epsilon‐1(EEF1E1) or p18, was reported as a tumour suppressor." (PMID 33538115, 2021). "The expression of EEF1E1 was positively correlated with body weight, BMI, tumor status, vascular invasion, AFP, logistic grade, T stage and pathological stage." (PMID 34282404, 2021). "In tumor tissue, overexpression of EEF1E1 was found in 25 datasets, whereas downregulation was observed only in five sets." (PMID 29342219, 2018). "In HCC, EEF1E1 mRNA and protein expression in tumor was statistically higher than normal tissue." (PMID 38972883, 2024). "Moreover, the correlation between EEF1E1 and tumor immune infiltration was analyzed using the gsva package with the ssgsea algorithm." (PMID 34282404, 2021). "In tumor tissues, four protective genes (JAK2, IL2RG, EEF1E1, and UBB) showed relatively low expression in the high‐risk group; in contrast, the expression of four risk genes (EPS8, FOXO1, STAT5A, and PAPPA) was more highly in the high‐risk group than that in the low‐risk group." (PMID 34825509, 2021). "No dataset showed significant difference in expression, between tumor and normal group, for EEF1E1." (PMID 29342219, 2018). "We also found that higher EEF1E1 expression was related to better survival in these two cancer types, however in many other cancer types (breast, lung, gastric, prostate, colorectal, liver) EEF1E1 was found to be overexpressed in tumor tissues and predicted poor survival (breast, lung, liver)." (PMID 29342219, 2018). "The result suggested that EEF1E1 and HDAC2 were associated with the progression of tumors where they show significant correlation with grade, stage, and T stage (P < 0.05), and the expression levels of EEF1E1 and HDAC2 were significantly higher in tumor tissue than in normal tissue." (PMID 36189258, 2022). "However, there was a significant upregulation of EEF1E1 mRNA levels in tumor tissues." (PMID 29342219, 2018). "EEF1E1 was recently mentioned as an independent prognostic factor in HCC and was correlated with the tumor immune microenvironment." (PMID 37999208, 2023). "Specifically looking at the cytoplasmic aaRS members, the genes that are preferentially amplified across most tumor types are TARS1, GARS1, MARS1, AIMP2, and AIMP3/EEF1E1." (PMID 33266490, 2020). "EEF1B2, EEF1G, EEF1D, EEF1E1 and EEF2, presented increased transcript levels in tumor group compared to normal, the most prominent being EEF1E1." (PMID 29342219, 2018). "The outcomes of the Kruskal–Wallis test unveiled a significant correlation between high expression levels of C1orf216 and EEF1E1 (p < 0.05), high expression of SRPRB (p < 0.01), high expression of RABGGTB (p < 0.001), and larger tumor size within the HCC cohort." (PMID 38972883, 2024). "However TCGA analysis revealed that in addition to EEF1E1, mRNA levels of EEF1A2, EEF1G, and EEF1D are also significantly upregulated in tumor tissues." (PMID 29342219, 2018). "However, significant overexpression of EEF1A2, EEF1G, EEF1D, EEF1E1 and EEF2 was seen in tumor tissues." (PMID 29342219, 2018).
cancer (13 papers, 2012 to 2025). A tumor composed of atypical neoplastic, often pleomorphic cells that invade other tissues. "It was showed that the EEF1E1 expression level in cancer is significantly higher than that of normal, p < 0.01." (PMID 34282404, 2021). "The results showed that the expression of EEF1E1 protein in cancer tissues was significantly higher than that in control tissue, p < 0.01." (PMID 34282404, 2021). "Overall, we see that in addition to EEF1A2; EEF1G, EEF1D, EEF1E1 and EEF2 are significantly upregulated in different cancer types and are associated with better and worse survival outcome in specific cancers." (PMID 29342219, 2018). "Among the components of ARSN, relatively higher cancer-associated network was shown by GARS, MARS, WARS, RARS, CARS, AIMP1 (SCYE1) and AIMP3 (EEF1E1) (green nodes)." (PMID 22952576, 2012). "Similarly, the expression of EEF1E1 protein in cancer tissues was significantly higher than that in adjacent tissues, p < 0.01." (PMID 34282404, 2021). "Meanwhile, the EEF1E1 protein level in cancer is significantly higher than paracancerous." (PMID 34282404, 2021). "Immunohistochemistry showed that EEF1E1 is highly expressed in cancer." (PMID 34282404, 2021). "There are a few aaRSs that are downregulated in multiple cancer types, including HARS2 (n = 6), WARS1 (n = 4), CARS2 (n = 4), IARS1 (n = 3), RARS2 (n = 3), VARS2 (n = 3), and AIMP3/EEF1E1 (n = 3), suggesting these aaRSs may possess certain specific cancer-inhibiting roles." (PMID 33266490, 2020). "RAC1, BAX, EEF1E1, and LPCAT1, four highly interacted genes, showed differential expression at gene levels in HCC and played essential roles in cancer cells." (PMID 37999208, 2023). "Higher expression of EEF1A2, EEF1B2, EEF1G, EEF1D, EEF1E1 and EEF2 was observed in most of the cancer types, whereas reverse trend was observed for EEF1A1." (PMID 29342219, 2018). "Keeping these lacunae in hindsight, we have undertaken a pan-cancer approach for comprehensive analysis of expression levels of seven elongation factors namely, EEF1A1, EEF1A2, EEF1B2, EEF1G, EEF1D, EEF1E1 and EEF2, using publicly available databases (Oncomine and TCGA)." (PMID 29342219, 2018). "In addition to EEF1A2, other translation factors EEF1B2, EEF1G, EEF1D, EEF1E1, and EEF2 were also found to be frequently overexpressed in different cancers." (PMID 29342219, 2018).
EEF1E1 also shares sentences with these, for which no sentence is quoted: chronic myeloid leukemia (2 papers); bladder cancer (1); breast carcinoma (1); colon carcinoma (1); diffuse large B-cell lymphoma (1); glioma (1); lung adenocarcinoma (1); lung carcinoid tumor (1); non-small cell lung carcinoma (1); oligodendroglioma (1); progeria (1); scleroderma (1); small cell lung carcinoma (1); squamous cell lung carcinoma (1); teratoma (1); virus infection (1).